TAS2R62P (taste 2 receptor member 62, pseudogene)
Synonyms: T2R62; TAS2R62; PS1
Gene: Unitary pseudogene on chromosome 7 (143,437,034 to 143,437,973, forward strand). Ensembl gene ENSG00000234066.
Diseases named in the same sentence as TAS2R62P in open-access papers:
TAS2R62P is named in the same sentence as 1 disease in open-access papers, as found by Europe PMC text mining. Sharing a sentence is not in itself a finding about the gene and the disease.
TAS2R62P shares sentences with these, for which no sentence is quoted: COVID-19 (1 paper).